IL13 (interleukin 13)
Diseases named in the same sentence as IL13 in open-access papers (continued):
Sharing a sentence is not in itself a finding about the gene and the disease.
anaphylaxis (10 papers, 2019 to 2026). An acute hypersensitivity reaction that occurs from exposure to an allergen. "We observed enriched representation of 15 anaphylaxis‐associated pathways and identified 15 genes involved in IgE/FcεRI signaling that were convergently modulated by IFNγ, IL‐33, IL‐4 + IL‐13, and TGFβ." (PMID 40926620, 2025). "Activation of the steroidogenic enzyme CYP11A1 was shown to be necessary for the development of peanut-induced intestinal anaphylaxis and IL-13 production in allergic mice." (PMID 32497050, 2020). "Distinct Tfh subsets, characterized by differential production of IL-4 and IL-13, may further determine whether IgE responses remain low-affinity or mature into high-affinity antibodies capable of driving anaphylaxis." (PMID 41917787, 2026). "However, Th2 cytokines such as IL-4, IL-5, and IL-13 are thought to promote allergic reactions including eosinophil infiltration and IgE production, which induce Th2-dependent antibodies and systemic anaphylaxis." (PMID 36499554, 2022).
Anxiety (10 papers, 2016 to 2025). Intense feelings of nervousness, tension, or panic often arise in response to interpersonal stresses. "Deficiency in meningeal-derived cytokines, such as IL-4, IL-13, and IL-17α, has been shown to impaired learning, memory, social, and anxiety-like behaviors." (PMID 36703978, 2022). "We found that the performance in semantic association of verbal fluency in patients post chemotherapy might be affected by the status of cancer, IL-13, and anxiety." (PMID 34073990, 2021). "Despite this, a significantly poorer performance in verbal fluency (SFT) was found in the post-C/T group compared to non-cancer controls; and it may be explained by IQ, anxiety, and IL-13 from the multivariate regression model." (PMID 34073990, 2021).
breast tumor (10 papers, 2014 to 2025). "OX40L-expressing DCs were found in primary breast tumor infiltrates and in vitro they drove the development of inflammatory Th2 cells (i.e., producing IL-13 and TNF-α)." (PMID 33042121, 2020). "MDA-231 breast tumor cells exposed to IFN-γ or IL-13 induced phosphorylation of STAT1 and STAT6, respectively." (PMID 24911872, 2014). "In this study, we examined the changes of ILC1, ILC2, and ILC3 frequency in innate immunity, CD4+ and CD8+ T cells in adoptive immunity, and the expression of their associated cytokines (IFN-γ, IL-4, IL-10, IL-13, and IL-22) in 4T1 and MC4-L2 breast tumor models." (PMID 39877637, 2025). "Importantly, in a xenograft mouse model, anti-TSLP or anti-OX40L neutralizing antibodies inhibited breast tumor growth and IL-13 production." (PMID 33042121, 2020). "Breast tumor cells treated with DOX were observed to release IL-33, which induced IL-13+ Th2 cells to produce IL-13." (PMID 34084160, 2021). "Breast tumors are infiltrated by Th2 cells that strongly express IL4 and IL13, and these cytokines promote tumor growth by directly interacting with tumor cells, inhibiting DC responses and regulating the expression of cancer cell differentiation markers." (PMID 34571811, 2021). "However, IL-4 and IL-13 do not directly mediate the tumor-suppressing effect of Th2 cells onto the breast tumor cells." (PMID 35657353, 2022).
chronic bronchitis (10 papers, 2005 to 2025). A type of chronic obstructive pulmonary disease characterized by chronic inflammation in the bronchial tree that results in edema, mucus production, obstruction, and reduced airflow to and from the lung alveoli. "In our previous studies, we successfully developed chronic bronchitis-like mucosa models including an increased number of mucus-producing cells by treating the PBEC-ALI models with 1 ng/mL IL-13." (PMID 39440037, 2024). "According to previous studies, in vitro stimulation with IL-13 induces mucus producing cell hyperplasia which is a characteristic feature of chronic bronchitis." (PMID 28107509, 2017). "The number of IL-13+ cells was elevated in the bronchial submucosa of smokers with chronic bronchitis compared to asymptomatic smokers." (PMID 23267696, 2012). "In alveolar macrophages from smoker patients with chronic bronchitis, IL-13 protein secretion was decreased in a dose-dependent manner with theophylline." (PMID 16083514, 2005). "Also, an increased proportion of cells expressing IL4 and IL13 has been found in smokers with chronic bronchitis compared to asymptomatic smokers." (PMID 40468357, 2025). "Exacerbations of chronic bronchitis are often accompanied by significant airway eosinophilia, characterized by the release of inflammatory mediators including interleukin-4 (IL-4), interleukin-5 (IL-5), and interleukin-13 (IL-13)." (PMID 39361621, 2024). "Increased SCGB1A1 levels in the sham exposed chronic bronchitis-like model compared to that of normal bronchial mucosa may be explained by the addition of IL13 to induce mucous production." (PMID 34564359, 2021). "Therefore, treating cell cultured under ALI conditions with IL-13, the development of a chronic bronchitis-like mucosa is expected." (PMID 28107509, 2017). "At the same time, we predicted increased protein levels of IL-13, a Th2 cytokine, which may contribute to mucus hypersecretion and chronic bronchitis in smokers and COPD patients." (PMID 25962837, 2015). "Although the participation of IL-13 and other Th2 cytokines in COPD, including chronic bronchitis, has also been reported in several studies, they may be not important contributors to CLCA1 expression in COPD." (PMID 22731784, 2012).
leishmaniasis (10 papers, 2014 to 2025). Infectious disease that is transmitted through the bite of hematophagous female phlebotomine sand flies. "Susceptibility to leishmaniasis has been extensively associated with anti-inflammatory cytokines, as demonstrated in IL-4, IL-6, IL-10 and IL-13 deficient BALB/c mice." (PMID 37691941, 2023). "Genetic mapping studies conducted in murine models have identified a genomic region that encompasses the IL4 and IL13 genes as a susceptibility region for leishmaniasis." (PMID 37908348, 2023). "Based on the findings from animal models of leishmaniasis that high levels of IL-13 render them susceptible to infection, we investigated whether any genotype of the SNVs studied may be related to high or low levels of plasma IL-13 to explain the susceptibility/protection to Lg-Cl." (PMID 37908348, 2023). "As of now, there exists only one study focused on the genetic determinants of IL13 in the context of leishmaniasis." (PMID 37908348, 2023). "This was confirmed in IL-13 transgenic C57BL/6 mice, which developed a susceptible phenotype to acute leishmaniasis with impaired IL-12 and IFN-γ production, whereas IL-13-deficient BALB/c mice remained comparatively resistant." (PMID 29176972, 2017). "Later on, they show a dramatic progression of disease, whereas IL-4-deficient mice are well protected; pointing to a protective role of IL-13 in leishmaniasis." (PMID 24475277, 2014). "The role of IL-13 in leishmaniasis progression is conflicting." (PMID 38918456, 2024). "Moreover, the overproduction of Th2 cytokines can result in chronic inflammation, as in leishmaniasis, where the activation of IL-4 and IL-13 results in pathogen expansion and chronic infection." (PMID 37569646, 2023). "Murine experimental models have demonstrated the significance of IL-13 in leishmaniasis." (PMID 37908348, 2023).
leukemia (10 papers, 2013 to 2026). A malignant (clonal) hematologic disorder, involving hematopoietic stem cells and characterized by the presence of primitive or atypical myeloid or lymphoid cells in the bone marrow and the blood. "THP-1 was a human leukemia monocytic cell line that had been extensively used to study macrophage functions, so we used PMA and IL-4/IL-13 to induce THP-1 cells into M2 phenotype macrophages in this study." (PMID 36641471, 2023). "In order to monitor similar changes in human leukaemia monocytic cell line, M1 and M2 status was induced in THP-1 cells by activation with LPS/INF-γ and IL-4/IL-13, respectively." (PMID 35884829, 2022). "In human differentiated THP-1 cells (a human leukemia monocytic cell line), knockdown of PGAM5 stimulated TNFα and IL-6 secretion in naïve macropahges and increased TNFα, IL-6 and IL-1β in macropahges treated with IL-4 and IL-13 (M2 macrophage)." (PMID 37605246, 2023). "In addition, GLA significantly reduced the release of histamine and β-hexosaminidase, calcium influx, cytokine (IL-4, TNF-α, IL-1β, IL-13, and IL-8) production in the RBL-2H3 (rat basophilic leukemia cells), and RPMCs (peritoneal mast cells) in vitro." (PMID 34007295, 2021). "Intriguingly, cytokine profiling from on-chip tests demonstrated that 4-1BBζ-CAR secreted more IL-13 (a Th2 cytokine), and CD28ζ-CAR and ICOSζ-CAR secreted more IL-10, whereas this is not the case for 2D tests with respective co-cultures of CAR T cell and leukemia blast." (PMID 37131801, 2023). "Intriguingly, cytokine profiling from on-chip tests demonstrated that 4-1BBζ-CAR secreted more interleukin (IL)-13 (a TH2 cytokine), and CD28ζ-CAR and ICOSζ-CAR secreted more IL-10, which may not be clearly observed in simple 2D tests with respective co-cultures of CAR T cells and leukaemia blasts." (PMID 40595437, 2025).
myocarditis (10 papers, 2011 to 2025). Myocarditis is a condition that is characterized by inflammation of the heart muscle (myocardium). "On the other hand, IL-13 had expressed protective effects in the induction of myocarditis, caused either by immunization with cardiac myosin peptide, or CB3 virus infection in BALB/c mice." (PMID 36674665, 2023). "IL-2 implicated in myocarditis, and IL-4, IL-6, and IL-13 implicated in fibrosis and cardiomyopathy are the other inflammatory interleukins suppressed by NP-6A4." (PMID 34220518, 2021). "IL‐13 deficiency mice develop into severe myocarditis in both coxsackievirus B3 (CVB3)‐induced model and experimental autoimmune myocarditis (EAM) model, manifested in decreased systolic and diastolic left ventricular functions and decreased survival." (PMID 33943014, 2021). "Similarly, IL13 deficiency leads to more severe cardiac inflammation compared to controls, resulting in dilated cardiomyopathy after experimentally induced myocarditis." (PMID 22590615, 2012). "It has been reported that reconstitution of HDAC11 reduced IL-13 expression, while inhibition of HDAC11 increased IL-13 expression in CD4+ T cells of heart tissue in patients with myocarditis." (PMID 35279683, 2022). "It is believed that IL‐13 consecutively contributes to regulating recruitment and differentiation of immune cells, chemokines secretion and fibrosis during the progression of myocarditis." (PMID 33943014, 2021). "In order to evaluate the role of M2 macrophages in the IL-13-attenuated CVB3-myocarditis, we isolated mouse macrophages from bone marrow of age-matched, isogeneic mice." (PMID 29245918, 2017). "Instead, administration with IL‐13 could significantly ameliorate the heart inflammation and cardiac injury caused by CVB3 induced myocarditis." (PMID 33943014, 2021). "Adoptive transfer to M2 macrophages mimicked the effects of IL-13 on protection from myocarditis, suggesting that the effects of IL-13 may be primarily through regulation of macrophage polarization." (PMID 29245918, 2017). "The inconsistency between the decreased protective IL-13 and the improved myocarditis by pIP-10-AT might be explained by an overwhelming beneficial effect of Th1 cytokine reduction to a relevant weak detrimental effect of solely Th2 cytokine (IL-13) decrease." (PMID 21445362, 2011). "Interestingly, IL-13 administration attenuated the detrimental effects of OVB3 on these parameters, suggesting that IL-13 may protect mouse heart function in CVB3-induce myocarditis." (PMID 29245918, 2017). "AAV9-IL9 showed remarkable enrichment over all other interleukins in both Pool 60 and Pool 15, and in combination with IL3, IL4, IL13, and IL15 (Pool 5), significantly improved CVB3-induced myocarditis." (PMID 35508525, 2022). "In this study, the pooled AAV9-mediated overexpression of 60 cytokines in a human Coxsackievirus-B3-induced myocarditis mouse model allowed the identification of five cardioprotective interleukins (IL9, IL3, IL4, IL13, and IL15)." (PMID 35508525, 2022). "Thus, IL-13 reduces T lymphocyte immunity and induces M2 macrophage polarization in CVB3-induce myocarditis." (PMID 29245918, 2017). "IL‐13 could decrease both T lymphocyte infiltration of the heart and activation of T lymphocytes in the spleen and influence the production of interferon (IFN)‐γ and IL‐17, which mediate the differentiation of macrophages or directly prevent from myocarditis." (PMID 33943014, 2021). "Like IL-13, adoptive transfer of M2 macrophages attenuated the detrimental effects of OVB3 on these parameters, suggesting that the effects of IL-13 on CVB3-myocarditis may be primarily through induction of M2 macrophage polarization." (PMID 29245918, 2017).
Nephropathy (10 papers, 2018 to 2025). A nonspecific term referring to disease or damage of the kidneys. "Th2 cytokines such as IL-4 and IL-13 are involved in renal diseases (podocyte disorders) that cause proteinuria, such as minimal change nephrotic syndrome (MCNS)." (PMID 40191205, 2025). "Elevated levels of IL-13 are present in the urine and serum of patients who have kidney disease, and are also associated with a proteinuria." (PMID 33968853, 2021). "Notably, Th2 cytokines, such as IL-4 and IL-13, as well as neutrophil- and macrophage-mediated inflammation, are also implicated in the progression of renal diseases, contributing to glomerular injury, proteinuria, and chronic kidney inflammation." (PMID 40191205, 2025). "Interleukin 13 (IL-13) was shown to stimulate podocyte protein trafficking and proteolysis in vitro, and overexpression of IL-13 in rats was found to induce an MCD-like nephropathy." (PMID 36672735, 2023). "These previous studies thus suggest that IL-13 functions in the pathogenesis of kidney disease, but the mechanism responsible for the increased IL-13 level is still unclear." (PMID 33968853, 2021). "A recent study used an interleukin-13 (IL-13) overexpression rat model of minimal change-like nephropathy and found that these rats had upregulated expression of Vav1." (PMID 29415466, 2018). "Recent studies found increased levels of IL-13 and IL-4 during the active phase of INS, and that IL-13 functions in the pathogenesis of kidney disease, but the mechanisms responsible for the increased level of IL-13 are still unclear." (PMID 33968853, 2021). "Another intriguing animal study directly addressed the role of IL-13 by overexpressing it in the rats and reported that an MCN-like nephropathy was induced, with changes in podocyte structure and gene expression similar to those seen in human diseases." (PMID 33330285, 2020). "In conclusion, our results indicate that the Th2 related-cytokine IL-13 is related to the pathogenesis of kidney disease but is not related to atopy, although the mechanisms responsible for the increased level of this cytokine remain unclear." (PMID 33968853, 2021). "Thus, the abnormal increase of Th2 cells and its related factor IL-13 in children with INS is not related to atopy, but is related to the pathogenesis of nephropathy." (PMID 33968853, 2021).
renal fibrosis (10 papers, 2019 to 2025). A final common manifestation of a wide variety of chronic kidney diseases characterized by glomerulosclerosis and tubulointerstitial fibrosis. "ILC2/IL‐4 or IL‐13/TGF‐β1 exacerbate renal fibrosis in DKD, which is defined by proteinuria and eGFR." (PMID 40801800, 2025). "Pro-fibrotic cytokines, including IL-7, IL-13, and IL-8, promote the expression of Thy-1 genes and sThy-1 release from renal interstitial fibroblasts, leading to renal fibrosis and ultimately the development of CKD." (PMID 37711613, 2023). "And Simvastatin can directly inhibit the STAT6 pathway activated by interleukin-13 (IL-13), thereby inhibiting the activation of myeloid fibroblasts and the development of renal fibrosis." (PMID 37781714, 2023). "Hypoxia‐inducible factor‐prolyl hydroxylase (HIF‐PHD) inhibitors alleviated renal fibrosis through reduced phosphorylation of p38MAPK in ILC2s; thus, M2 polarisation followed by IL‐4/IL‐5/IL‐13 production was decreased, suggesting the pathogenesis role of ILC2/cytokines/M2 in renal fibrosis." (PMID 40801800, 2025). "IL-33 promotes renal fibrosis through macrophages and increases secretion of IL-13 and TGF-β1." (PMID 35046838, 2021). "The ILC2-related Th2 cytokines (IL-4, IL-13) promote the expression of TGF-β1, leading to renal fibrosis via Smads and MAPKS signaling pathways." (PMID 31355294, 2019). "Our study found that the secretion of the Th2 cytokines (IL-4, IL-13) and the upregulation of TGF-β1 were the key factors leading to renal fibrosis in DKD." (PMID 31355294, 2019). "At least, MST1/2 inhibition could reduce the IL-4+IL-13-induced activation of STAT6 and MEK/ERK in macrophage independent and dependent of YAP, and MST1/2 inhibition impaired M2 polarization and renal fibrosis." (PMID 38250155, 2024). "Moreover, the sustained release of inflammation-associated fibrotic cytokines such as transforming growth factor-β (TGF-β) and interleukin-13 (IL-13) can trigger epithelial–mesenchymal transition (EMT), potentially leading to renal fibrosis and chronic renal insufficiency." (PMID 38339031, 2024). "Interestingly, renal fibrosis and inflammatory mediators, including TGF-β, angiotensin II, PDGF-B, and IL-4 and IL-13, could upregulate the expression of periostin." (PMID 34992536, 2021). "Since two independent studies suggested increased numbers of ILC2s and type 2 cytokines (IL-4, IL-5, IL-13) in the peripheral blood of patients suffering from CKD due to type 2 diabetes, it can be speculated that ILC2s might be a marker for renal fibrosis in human CKD." (PMID 32063905, 2020). "Besides, it has been reported that in IL-4 and IL-13-treated HK-2 cells, the JAK-STAT6 signaling pathway was sufficiently activated to promote EMT, mesangial cell proliferation, ECM deposition, and foot cell damage, eventually leading to renal fibrosis." (PMID 31355294, 2019).
type 1 diabetes (10 papers, 2008 to 2024). "In addition, the significance of IL13 polymorphisms has been documented in clinical phenotypes that serve as risk factors for MI, such as type-1 diabetes mellitus, hypertension, and dyslipidemia." (PMID 39088580, 2024). "In baseline samples from all the participants, GAD-specific IL-13 responses are present at a low frequency in new-onset type 1 diabetes, with nine out of 46 (20%) participants showing a response." (PMID 32248243, 2020). "Both 1,25(OH)2D3 and TX527 also reduced the Th2 cytokines IL-13 and IL-4 and IL-5 (data not shown) in cultures from control and type 1 diabetes donor T cells, albeit not always statistically significant." (PMID 25279717, 2014).
bacteremia (9 papers, 2013 to 2025). "However, IL-13 has also been associated with protection against murine bacterial sepsis and infections such as listeriosis." (PMID 36060742, 2022). "Given our observations of increased intestinal permeability and bacteremia in baso IL-4/IL-13 (−) mice, we assayed plasma MPO and NE, antimicrobial effectors frequently used as markers for neutrophil activation." (PMID 38780542, 2024). "Specifically, basophil-dependent IL-4/IL-13 control MC activation and prevent infection-induced intestinal barrier damage and bacteremia, perhaps via regulation of eosinophils, macrophages, and Th17-mediated inflammation." (PMID 38780542, 2024). "This rarity is attributed to the distinct pathophysiology of parasite-induced systemic inflammation, which typically involves type-2 immune responses (IL-4/IL-5/IL-13 dominance) rather than the cytokine storms characteristic of bacterial sepsis." (PMID 41488892, 2025).